ALB (albumin)
Diseases named in the same sentence as ALB in open-access papers (continued):
Sharing a sentence is not in itself a finding about the gene and the disease.
Hypertension (continued). "Our study identified thirteen features: HbA1c, Crea, AST, Lp(a), Apo Ai, hypertension, smoking status, age, FIB, HDL-C, ALB, Glu and TP." (PMID 40475993, 2025). "Boruta algorithm screening: 500 iterations were conducted, and 14 key variables were confirmed through importance scores: BMI, neutrophils, LMR, PNI, lymphocytes, albumin, platelets, NLR, AISI, ALI, SII, hypertension, multiple pregnancies, and smoking." (PMID 40606469, 2025). "For grade III-IV aGVHD, hypertension, renal injury, fragmented red blood cells, LDH, TBIL, platelet counts, hemoglobin, and albumin were significant." (PMID 41438980, 2025). "This nomogram prediction model consists of five factors: hypertension, SOFA score, tidal volume, respiratory rate, and serum albumin level." (PMID 40225039, 2025). "The findings showed that there were significant differences in gender, PIR, BMI, hypertension, Hb, HCT, MCH, RDW, and albumin between the High and Low CRP groups (P < 0.05)." (PMID 40087374, 2025). "The identified factors—age, hypertension, prior cerebrovascular events, ASA classification, intraoperative BPV, and albumin levels—highlight the multifactorial nature of POD and underscore the importance of individualized perioperative care." (PMID 40301442, 2025). "This association persisted after adjusting for potential confounders, including age, hypertension, stroke, intracerebral hemorrhage, ASA classification, Surgery type and albumin, (adjusted OR: 1.14, 95% CI 1.09–1.19, p = 0.001)." (PMID 40301442, 2025). "Higher NHR values were correlated with age, sex, hypertension, intraventricular hemorrhage, GCS score, glucose levels, C-reactive protein, absolute lymphocyte count, albumin levels, and absolute monocyte count." (PMID 40800139, 2025). "The final model (Model 3) identified four robust independent predictors alongside hypertension history: Killip class III/IV (OR = 2.99), elevated NEU% (OR = 1.05), Hyperkalemia (K+) (OR = 1.70), and higher serum Albumin (ALB) (OR = 0.92)." (PMID 41409354, 2025). "Cox analysis identified hypertension, cardiac insufficiency, renal injury, fragmented red blood cells, LDH, platelet counts, hemoglobin, and albumin as significant mortality factors for TA-TMA." (PMID 41438980, 2025). "The RF model comprised ALT, DM, age, HDL-C, ALB, TG, fasting insulin, AST, LDL-C, creatinine, body weight, PLT, height, HbA1c, total bilirubin, hypertension, BMI, TC, uric acid, and sex." (PMID 40361915, 2025). "Dependent factors included markers of hypertension (systolic and diastolic blood pressure) or CKD (creatinine, cystatin C, urinary albumin/creatinine), adjusted for body mass index." (PMID 40426748, 2025). "Risk factors for weaning failure in critically ill patients living at high altitudes included a history of hypertension, higher SOFA score, lower tidal volume, higher respiratory rate, and lower serum albumin levels." (PMID 40225039, 2025). "For the linear SVM model, the selected variables were BMI, body weight, height, ALT, age, AST, creatinine, uric acid, fasting insulin, DM, HbA1c, PLT, hypertension, HDL-C, TC, TG, ALB, LDL-C, sex, and total bilirubin." (PMID 40361915, 2025). "After adjusting for age, gender, hemoglobin, albumin, NAFLD, hypertension, history of smoking, history of alcohol consumption, and BMI, ln(Ins60/ApoA) was an independent influence factor for ACR ≥ 30 mg/g (OR = 2.778, p = 0.015)." (PMID 41140685, 2025). "Statistical differences were observed between the two groups in terms of age, history of hypertension BMI, red blood cell (RBC) count, platelet count, and admission albumin levels (P < 0.05)." (PMID 40687754, 2025). "Patient-related factors contributing to the score included preoperative albumin levels <3.0 g/dL (3 points), ASA score per unit increase (3 points), hypertension (4 points), cardiovascular disease (3 points), and cerebrovascular disease (4 points)." (PMID 40002606, 2025).
Hypertension (continued). "In our study, ISI remained a significant predictor even after adjusting for potential confounding factors such as age, gender, hypertension, LDL cholesterol, and albumin, indicating that this index directly reflects acute myocardial damage." (PMID 40941674, 2025). "We found that the risk factors for weaning failure in critically ill patients living at high altitudes included a history of hypertension, higher SOFA score, lower tidal volume, higher respiratory rate, and lower serum albumin levels." (PMID 40225039, 2025). "Data retrieved included anthropometric variables (weight, BMI, EWL%, TWL%), nutritional/metabolic outcomes (hemoglobin, protein, vitamin B12, albumin, Ca, HbA1c), and obesity-related conditions (T2DM, hypertension, depression, PCOS, OSA, and GERD)." (PMID 40624299, 2025). "The AdaBoost model was built using ALB, LDL-C, DM, total bilirubin, HbA1c, HDL-C, TG, creatinine, age, ALT, TC, BMI, fasting insulin, body weight, AST, PLT, uric acid, height, sex, and hypertension." (PMID 40361915, 2025). "To mitigate this, baseline laboratories were obtained primarily under standardized procedures at GPHCM, and we adjusted for covariates related to volume and nutrition (e.g., eGFR, serum albumin, use of diuretics and ACEI/ARB, and presence of hypertension)." (PMID 41244046, 2025). "The GP model was constructed using the following variables: ALT, body weight, PLT, height, age, uric acid, creatinine, BMI, total bilirubin, AST, TG, ALB, fasting insulin, DM, HbA1c, LDL-C, TC, HDL-C, sex, and hypertension." (PMID 40361915, 2025). "ALB is the most abundant circulating protein in blood, which is protective in several diseases, including CHD, heart failure, hypertension, atrial fibrillation, and peripheral artery disease." (PMID 40371078, 2025). "For instance, steroid treatment, surgery, hypertension, cardiovascular diseases, autoimmune diseases, acute infections, acute kidney and liver disorders, and diagnosis of other cancer types may affect neutrophil, platelet, hemoglobin, albumin, and lymphocyte values." (PMID 39061000, 2024). "These factors include age, hypertension, sepsis or septic shock, renal injury, white blood cell count, blood calcium levels, C-reactive protein (CRP), creatinine, albumin, and hemoglobin (p < 0.05)." (PMID 38903514, 2024). "We had the following inputs included in the ANN model for the imputed dataset; DPP4-I groups, hypertension, hypothyroidism, age, baseline LDL-C, calcium, uric acid, urine albumin and eGFR." (PMID 39186745, 2024). "These factors included age, albumin levels, NRS2002 score, history of anemia and hypertension, emergency surgery, operative time, intraoperative bleeding and SPO2 levels, tumor T stage, tumor lymph node invasion, and tumor PNI (P<0.05)." (PMID 39664192, 2024). "Patients with PPCs had more cases of hypertension, a higher ASA class and lower albumin level (p < 0.05)." (PMID 39210309, 2024). "Proteins with high disease scores (76–100% confidence) for both hypertension and chronic kidney disease included angiotensinogen (AGT), albumin (ALB), apolipoprotein L1 (APOL1), and uromodulin (UMOD)." (PMID 38402394, 2024). "We found that age, gender, physical activity, eGFR, hypertension, and CVD were significant influencers of the albumin-adjusted serum calcium-NAFLD relationship (p for interaction all <0.05)." (PMID 38505748, 2024). "In secondary analyses, serum albumin and periventricular WMH along with age, sex, diagnoses, BMI, and hypertension were considered for hierarchical contribution to variance in performance in 4 cognitive domains." (PMID 38260299, 2024). "We found that physical activity, eGFR, hypertension, and CVD were also important influences on albumin-adjusted serum calcium in relation to NAFLD." (PMID 38505748, 2024). "The distributions of sex, age, race, BMI, hypertension, ALT, serum creatinine, serum total protein, and serum albumin varied significantly between the quartiles of BEOC." (PMID 38835754, 2024).
Hypertension (continued). "Significant differences were observed between the two groups in terms of age, hypertension, sepsis, renal injury, and various laboratory indicators, including WBC, PLT, Ca2+, CRP, hemoglobin, albumin, and creatinine (P<0.05)." (PMID 38903514, 2024). "Models were adjusted for age, gender, race, education level, PIR, serum cotinine, BMI, physical activity, alcohol, hypertension, hyperuricemia, TC, HDL-C, albumin, creatinine, BUN, heart failure/HbA1c." (PMID 37996718, 2024). "Although the underlying mechanisms linking serum albumin trajectories to the development of hypertension have not been fully elucidated, this finding provides some evidence that the optimal state of serum albumin may be a pattern of high stability within the normal range." (PMID 38779492, 2024). "After adjusting for age, gender, hypertension, dyslipidemia, chronic kidney disease (CKD), smoking status, BMI, HDL cholesterol, TC, and albumin, the weighted smooth curve fitting also showed that TyG index was still linearly related to the risk of no-reflow." (PMID 39346096, 2024). "With higher TFQI quartiles, the age, BMI of the population were lower, while systolic blood pressure, FPG level, triglycerides, platelet count, albumin level were higher, as well as ALT level and the percentage of patients with NAFLD and hypertension." (PMID 39744179, 2024). "Proteins including AGT, ALB, APOL1, and UMOD had the highest disease scores (76–100% confidence) for CKD and hypertension." (PMID 38402394, 2024). "Next, we built a multiple logistic regression model with primary vaccination status as the outcome and age, hypertension, CKD, and malignancy in the medical history, as well as serum albumin at hospital admission as potential covariates." (PMID 37755581, 2024). "There was a higher prevalence of hypertension CRF (3.6% vs. 18.8%, p=0.034) in the lower albumin group than in the higher albumin group." (PMID 37082727, 2023). "We compared the baseline characteristics including age, sex, hypertension, T2DM, weight, BMI, smoking, drinking, albumin, hemoglobin, tumor location, TNM stage, and tumor size between the remission and non-remission groups." (PMID 37914834, 2023). "The analysis was adjusted for various factors, including age, sex, race, marital status, PIR, BMI, education level, work activity, alcohol consumption, smoking status, urinary albumin, LDL, HDL, hypertension, and dietary calcium intake." (PMID 37576036, 2023). "The baseline characteristics encompassed age, sex, body mass index (BMI), smoking, drinking, hypertension, type 2 diabetes mellitus (T2DM), neoadjuvant therapy, LDH, albumin, hemoglobin, LAR, tumor location, tumor node metastasis (TNM) stage, and tumor size." (PMID 37770882, 2023). "Age, gender, eGFR, urine ACR, albumin, hemoglobin, medical history of T2DM, and hypertension were included in the final model." (PMID 36836039, 2023). "Clinical characteristics and factors that are independently correlated with the average daily dose are age (p = 0.0005), body surface area (p < 0.001), hypertension (p = 0.0089), CHF (p = 0.0345), and levels of serum albumin (p = 0.0163)." (PMID 38066032, 2023). "For those patients with hypertension in the severe group, levels of Cr, PCT, CRP, and ESR were significantly increased while levels of PLT and ALB were decreased, where levels of CRP, ESR and ALB were varied both quantitatively and as a categorical variable." (PMID 37790212, 2023). "Some differences existed between groups concerning various covariates, including age, sex, weight, smoking status, drinking status, fibrinogen, ALB, ALP, UA, GLU, CREA, Urea, PLT, hypertension, ischemic cerebrovascular disease, CHD, DM (all p < 0.05)." (PMID 37007769, 2023). "Based on the literature, we performed Cox survival analysis using age at dialysis, sex, entry year, DM, hypertension, hepatitis, postdialysis BW, nPCR, UF/BW ratio, creatinine, hemoglobin, WBC, albumin, AC, log-transformed cholesterol, and phosphorus." (PMID 37264037, 2023).
Hypertension (continued). "The two MHD groups had a higher prevalence of hypertension, blood creatinine, BUN, PTH, blood phosphorus, FGF23, and D-serine than the control group, but also lower Hb, RBC, and ALB (all P < 0.01)." (PMID 36649363, 2023). "Therefore, serum albumin may reflect angiogenesis activity which in turn may prevent hypertension." (PMID 37700384, 2023). "Backward stepwise cox regression identified hypertension, histological grade, TNM stage, preoperative albumin, preoperative LMR and dynamic LMR change as independent predictors for survival estimation." (PMID 37519800, 2023). "Meanwhile, the proportions of patients with serum ALB<LLN, PLT<LLN, ACA and/or anti-CENP-B-positive, cirrhosis, and hypertension in the PBC plus T2DM group were significantly higher than those in the non-T2DM group (all P<0.05)." (PMID 38027142, 2023). "After adjustment for sex, age, hypertension, DM, APTT, PLT, CREA, ALP, and ALB, the OR value was also stable (OR, 1.14; 95% CI, 0.99–1.3)." (PMID 37007769, 2023). "Along with the hypertension, NAME animals also exhibited a markedly increased urine albumin excretion rate, a clear evidence of renal impairment." (PMID 37633958, 2023). "With death as the outcome, age, gender, ethnicity, PIR, hypertension, DM, vitamin C, ALP, ALB, SCR, and NFS scores were finally selected for further adjustment using LASSO regulation." (PMID 36983735, 2023). "There were significant differences between the two groups in gender, hypertension ratio, baseline proteinuria, NAG, RBP, serum albumin, Scr, cholesterol, triglyceride, and positive anti-PLA2R ratio." (PMID 35820795, 2022). "Baseline information including age, sex, BMI, smoking, drinking, hypertension, T2DM, CHD, pre-operative hemoglobin, pre-operative albumin and TNM stage were compared before and after 1:1 ratio PSM." (PMID 35799152, 2022). "In a study of an Asian population with hypertension combined with CKD, sacubitril valsartan reduced systolic blood pressure by 20.5 mm Hg and urinary albumin/creatinine ratio (UACR) by a significant 15.1% in patients with hypertension combined with CKD." (PMID 35600466, 2022). "The albumin and WBC decreased were the most common AEs, occurred in 42.1%, 37.7% of patients, respectively, and hypertension (8.8%), proteinuria (3.6%), and WBC decreased (4.4%) were the most frequent grade 3-4 AEs." (PMID 35860582, 2022). "Meanwhile, patients in high PDW group had a higher rate of females and higher levels of serum urea nitrogen, uric acid, creatinine, albumin, and phosphorus, but lower dialysis vintage, cholesterol, RRF, creatinine, and a lower rate of hypertension." (PMID 36285366, 2022). "As the MEST-C score increased, there were increased rates of hypertension; higher creatinine, uPCR, and phosphate values; increased immunosuppression use and requirement for RRT; along with lower haemoglobin, eGFR, albumin and calcium values." (PMID 36048745, 2022). "There were statistically significant differences between the DR group and the NDR group in terms of gender, prevalence of hypertension, course of T2DM, renal (BUN, UALB, UCr, UACR) and liver (ALT, AST, ALB, and TP) function-related indicators (P < 0.05)." (PMID 35672376, 2022). "We observed a decrease in the differences in factors such as the prevalence of DM, hypertension, SBP, serum albumin and uric acid level." (PMID 36086712, 2022). "Analysis was adjusted for age, gender, ethnicity, smoker, drinker, DM, hypertension, HF, CHD, stroke, cancer, BMI, hemoglobin, platelets, LDL-C, triglyceride, albumin, and eGFR." (PMID 35300686, 2022). "Demographic data with preoperative weight, BMI, hypertension (HTN), DM (HbA1C), Hb, iron, calcium, albumin, vitamin D, and parathormone levels (PTH) were recorded." (PMID 35488110, 2022).
Hypertension (continued). "Among male patients, alcohol consumption, hypertension, age, DBP, WBC, albumin, Cr, eGFR, TG, TC, LDL-C, HDL-C, EF, statins, CTO, ML, and the number of lesional vessels were significantly different among the three groups (all p <0.05)." (PMID 35369313, 2022). "The combination of albumin, PAPP-A, total bilirubin, and eGFR levels appears to be optimal for predicting pregnancy-related hypertensive disorder severity." (PMID 36140589, 2022). "In the univariable Cox hazards model analysis, BVAS, FFS, serum albumin levels, ALT levels, hypertension, and FIB-5 < 0.82 and < −0.42 at diagnosis were significantly associated with the occurrence of ESRD during the follow-up period." (PMID 33611672, 2021). "Another study on the hypertension population suggested that 24 h DBP and IDH only relate to the urinary albumin creatinine ratio in patients below 55-years-old." (PMID 33619233, 2021). "Risk factors for severe infection include obesity (body mass index [BMI] ≥ 28 kg/m2), type 2 diabetes, hypertension, elevated lactate dehydrogenase (LDH > 250 U/L), C-reactive protein (CRP > 10 mg/L), and albumin (ALB < 35 g/L)." (PMID 34200036, 2021). "Lastly, cluster 3 was mainly characterized by older age, more history of hypertension, more use of ACEI/ARB, lower eGFR, higher serum potassium, magnesium, albumin, and calcium." (PMID 34829467, 2021). "Compared with the normotension group, the following biochemical markers were higher in the hypertension group: SUA; blood glucose; ALT; AST; total cholesterol; triglycerides; LDL; urinary albumin/creatinine; and serum creatinine." (PMID 34869624, 2021). "The evisceration was associated with the following preoperative factors: old age, high body mass index (BMI), hypertension, smoking, any comorbidity, high ASA scores (ASA 3 and 4), and low preoperative albumin level." (PMID 32927929, 2021). "An increased glomerular basement membrane permeability to albumin in terms of microalbuminuria was commonly observed in post-AKI episodes and in patients with hypertension." (PMID 34945056, 2021). "Age, shortness of breath, comorbidities including hypertension, heart disease, and chronic obstructive pulmonary disease, higher NLR, lower albumin levels, and multiple mottling and ground-glass opacity were associated with progression." (PMID 32730223, 2020). "Patients who died as a result of CV death were more frequent to have a history of hypertension, prior CVD, higher levels of VP, albumin and creatinine." (PMID 32296707, 2020). "Exceptions were urine albumin to creatinine ratio for CKD and hypertension patients and HbA1c for hypertension patients, which are recommended by guidelines but were ordered ‘never’ or ‘sometimes’ by most GPs." (PMID 33278890, 2020). "Logistic analysis showed that the risk of DKD increased with the upregulation of ESR, even after adjustment for age, gender, hypertension, hemoglobin, TC, HDL, ALB, GLB, HbA1c, and the usage of RAS inhibitor." (PMID 32660469, 2020). "After K–M analysis, we found that age, hypertension, T2DM, N/L, CRP, AST, ALB, BUN and D-dimer had effects on patient outcomes." (PMID 32631365, 2020). "Serum IS levels were positively correlated with systolic BP, diastolic BP, hypertension history, CVD history, levels of albumin, BUN, Scr and hsCRP and negatively correlated with eGFR, hemoglobin, HDL-c and urine protein levels (all with p < 0.05)." (PMID 33191829, 2020). "There was a significant relation between hypertension comorbidity with the albumin excretion rate and grading diabetic retinopathy where the A3 and proliferative diabetic retinopathy (PDR) percentages were higher in the hypertension group at 68.8% and 54.5%." (PMID 32509246, 2020). "In the univariate analysis, LDL-cholesterol SD was significantly positively correlated with DM, hypertension, fasting glucose, phosphorous, UPCR, and the use of statins, and negatively correlated with albumin." (PMID 29423043, 2018).